AGBL3 (AGBL carboxypeptidase 3)
Description:
Metallocarboxypeptidase that mediates deglutamylation of tubulin and non-tubulin target proteins. Catalyzes the removal of polyglutamate side chains present on the gamma-carboxyl group of glutamate residues within the C-terminal tail of tubulin protein. Specifically cleaves tubulin long-side-chains, while it is not able to remove the branching point glutamate. Also catalyzes the removal of polyglutamate residues from the carboxy-terminus of non-tubulin proteins such as MYLK. May catalyze the hydrolysis of aspartate from the carboxy-terminus of target proteins. Does not show detyrosinase or deglycylase activities from the carboxy-terminus of target proteins. [Isoform 2]: Metallocarboxypeptidase that mediates tubulin deglutamylation.
Synonyms: CCP3; MGC32955
Tractability: No criterion of Open Targets' tractability assessment is met for any kind of drug.
Gene: Protein-coding gene on chromosome 7 (134,986,508 to 135,147,963, forward strand). Ensembl gene ENSG00000146856.
Subcellular location: Cytoplasm, cytosol
Subcellular location (Human Protein Atlas): Cytosol
Pathways (Reactome):
Metabolism of proteins: Carboxyterminal post-translational modifications of tubulin
Gene Ontology:
Molecular function: metallocarboxypeptidase activity; tubulin binding; zinc ion binding
Biological process: proteolysis
Cellular component: centriole; cytoplasm; microtubule cytoskeleton; cytosol
Genetic constraint (gnomAD): Loss-of-function variants: 44 observed, 63.35 expected, observed/expected ratio (o/e) 0.69, 90% interval 0.55 to 0.89. The upper end of that interval is the gene's LOEUF score, 0.89, which puts it in group 3 of 6, group 1 being the genes least tolerant of losing a copy. Missense variants: 784 observed, 949 expected, observed/expected ratio (o/e) 0.83, 90% interval 0.78 to 0.88. Synonymous variants: 292 observed, 320.32 expected, observed/expected ratio (o/e) 0.91, 90% interval 0.83 to 1.
Homologues: Orthologues: chimpanzee AGBL3 (99% identical), macaque AGBL3 (98% identical), dog AGBL3 (84% identical), pig AGBL3 (79% identical), rabbit AGBL3 (78% identical), rat Agbl3 (77% identical), mouse Agbl3 (77% identical), tropical clawed frog agbl3 (47% identical). Paralogues in human: AGBL2 (41% identical), AGTPBP1 (25% identical), AGBL1 (23% identical), AGBL5 (18% identical), AGBL4 (16% identical).
Diseases named in the same sentence as AGBL3 in open-access papers:
AGBL3 is named in the same sentence as 17 diseases in open-access papers, as found by Europe PMC text mining. Sharing a sentence is not in itself a finding about the gene and the disease. The quoted sentences say what the papers report.
amyotrophic lateral sclerosis (1 paper, 2025). Amyotrophic lateral sclerosis (ALS) is a neurodegenerative disease characterized by progressive muscular paralysis reflecting degeneration of motor neurons in the primary motor cortex, corticospinal tracts, brainstem and spinal cord. "Our bioinformatics analysis revealed that the interaction network composed of LILRA5, HNRNPL and AGBL3 was significantly enriched in functions such as’ RNA splicing regulation ‘and’ metal peptidase activity ‘, and was closely related to the ‘amyotrophic lateral sclerosis pathway (hsa05014)’." (PMID 41379792, 2025).
osteoporosis (1 paper, 2025). A condition of reduced bone mass, with decreased cortical thickness and a decrease in the number and size of the trabeculae of cancellous bone (but normal chemical composition), resulting in increased fracture incidence. "Bioinformatics analysis identified LILRA5, HNRNPL and AGBL3 as common key genes for Osteoporosis and stroke, and these genes were highly effective in diagnosing both diseases." (PMID 41379792, 2025). "After identifying LILRA5, HNRNPL, and AGBL3 as common hub genes for Osteoporosis and stroke, their synergistic regulatory mechanisms further confirm the molecular basis of comorbidity." (PMID 41379792, 2025).
infection (4 papers, 2013 to 2022). The state of being infected such as from the introduction of a foreign agent such as serum, vaccine, antigenic substance or organism. "Upregulation of DNAH17 and AGBL3 post-ChiLCV exposure in the present study might be due to the manipulation of B. tabaci genes by ChiLCV to facilitate the infection and circulation of the virus within the vector." (PMID 35572639, 2022).
AGBL3 also shares sentences with these, for which no sentence is quoted: rheumatoid arthritis (6 papers); tumor (4); Arthritis (3); autoimmune disease (1); Autoimmunity (1); Crohn disease (1); inflammation (1); joint disease (1); Obesity (1); rheumatic diseases (1); Stroke (1); synovitis (1); ulcerative colitis (1); virus infection (1).